CTNNB1 (catenin beta 1)
Diseases named in the same sentence as CTNNB1 in open-access papers (continued):
Sharing a sentence is not in itself a finding about the gene and the disease.
ovarian carcinoma (continued). "Clinicopathologically, a dualistic model of ovarian cancer has been proposed: Type I tumors, comprised of low-grade serous, low-grade endometrioid, mucinous, and clear cell carcinomas, typically possess mutations in KRAS, PTEN, and CTNNB1." (PMID 35159108, 2022). "Notably, phosphosites (p.S29/Y30/T40/T41/T42) near the section-terminus of the CTNNB1 protein were commonly seen in breast and ovarian cancers (p.T41 was also observed in UCEC), and p.S675 was detected in substantial numbers of samples in all 5 cancers." (PMID 33875650, 2021). "To exemplify the power of NeDRex to extract biologically meaningful pathways from starting seeds, we used the ovarian cancer (OC) associated genes from NeDRexDB (AKT1, ALPK2, CDH1, CTNNB1, EPHB1, OPCML, PIK3CA, PRKN) and constructed disease module using the MuST algorithm." (PMID 34824199, 2021). "Interestingly, mutations typically associated with lower grade (Type I) ovarian cancers such as PIK3CA (0.66% cases mutated) and CTNNB1 (0.6% cases mutated) were also nominated as drivers despite having extremely low frequency." (PMID 23383675, 2012). "Mutations in CTNNB1 (β-catenin) are identified in 16%–54% of endometrioid ovarian cancer patients, and other mutations in APC, AXIN1, and AXIN2, which are key downstream proteins of the Wnt/β-catenin pathway, are also found in different types of ovarian cancer." (PMID 36185280, 2022). "Recent research has also shown that alterations in the genome region of CTNNB1 and RPA2 were closely related to the occurrence of ovarian cancer." (PMID 25803614, 2015). "Interestingly, it has been shown that the FDA-approved Wnt inhibitor pyrvinium pamoate, which down-regulates CTNNB1, synergizes with the PARP inhibitor olaparib in ovarian cancer cells and PDX models." (PMID 34439123, 2021). "Among these, CTNNB1, CDH1, XRCC5 are important ovarian cancer genes." (PMID 25803614, 2015). "Notably, expression levels of RPS6, RPL12, CTNNB1, RPL7, RPS2, and CALM3 did not have any impact on the survival of ovarian cancer patients." (PMID 39309198, 2024).
medulloblastoma (46 papers, 2009 to 2025). A malignant, invasive embryonal neoplasm arising from the cerebellum. "In previous studies, fifteen percent of cases analyzed underwent Wnt activation among medulloblastomas, and seventy-three percent of those cases had CTNNB1 mutations." (PMID 40564017, 2025). "The WNT-activated PB harbored a truncating DROSHA mutation characteristic for miRNA-altered PB and a CTNNB1 mutation typically seen in WNT-activated medulloblastomas." (PMID 41291966, 2025). "For instance, the CTNNB1 gene mutation can result in 90% WNT-activated medulloblastoma, which can induce alterations in the amino acid residues at the phosphorylation site of β-catenin, and LEF1 can form a transcriptional complex with β-catenin in the nucleus." (PMID 39881334, 2025). "According to the COSMIC catalog, all medulloblastoma patients displaying a CTNNB1 mutation within their catalog underwent a missense substitution mutation at the gene." (PMID 40564017, 2025). "Immunohistochemical detection of ALK has been postulated to be of significant value in the identification of WNT-activated medulloblastomas, complementing methods like CTNNB1 gene mutation and β-catenin nuclear reaction analysis." (PMID 38339401, 2024). "In the present study, we aimed to analyze the frequency of CTNNB1 mutations in WNT-activated medulloblastomas in a large Latin Iberian medulloblastoma cohort." (PMID 37746264, 2023). "From the remaining 33 WNT-activated cases (24 from Brazil, seven from Portugal, and two from Argentina), we detected CTNNB1 mutation in 24 (73%) cases, and nine (27%) medulloblastomas were CTNNB1 wild type." (PMID 37746264, 2023). "Our in-silico analysis of CTNNB1 mutations at cBioPortal showed that 13% (7/53) of WNT-activated medulloblastomas are CTNNB1 wild type." (PMID 37746264, 2023). "In our Latin-Iberian series of 24 CTNNB1 mutant medulloblastomas, we found a total of 25 pathogenic variants in the hotspot region of the exon 3, being 24 missense mutations, and one in-frame deletion." (PMID 37746264, 2023). "In the present study, we report for the first time, the frequency of CTNNB1 mutations in WNT-activated medulloblastomas in a large cohort of Latin-Iberian patients." (PMID 37746264, 2023). "Association of CTNNB1 status with clinicopathological features of 33 WNT-activated medulloblastomas from a Latin-Iberian population." (PMID 37746264, 2023). "For patients with WNT-activated medulloblastomas CTNNB1 wild type, referral for genetic risk cancer assessment and germline APC sequencing is recommended." (PMID 37746264, 2023). "The in silico analysis of medulloblastomas from the North American and European (NAM/EU) populations reveals 47 CTNNB1 variants in 46 WNT-activated medulloblastomas, with all variants being located in the exon 3 of the CTNNB1 gene." (PMID 37746264, 2023). "Landmark genomic studies have shown that 97% of WNT-driven medulloblastomas can be explained by somatic mutations in the CTNNB1 gene (~90%) and germline mutations in APC (~10%), which are mutually exclusive." (PMID 37746264, 2023). "WNT-activated subgroup medulloblastoma occurs in children, coincides with CTNNB1 mutation, and shows the best prognosis among the tumors." (PMID 37749662, 2023). "Among the 40 WNT-activated medulloblastomas included in the present study, we successfully evaluated CTNNB1 mutations in 33 cases and found 73% (24/33) of CTNNB1-mutated cases and 27% (9/33) CTNNB1 wild type." (PMID 37746264, 2023). "The aim of this study was to report the frequency of CTNNB1 mutations in WNT-activated medulloblastomas in a Latin-Iberian population and correlate with their clinicopathological characteristics." (PMID 37746264, 2023). "We have analyzed a panel of 88 pediatric medulloblastoma tumors for exon 3 mutations from the CTNNB1 gene and identified eight missense point-mutations and one in-frame deletion." (PMID 35053583, 2022).
medulloblastoma (continued). "CTNNB1 mutations are present in 90% of WNT-activated medulloblastomas; mutations in β-catenin, APC and AXIN1 have also frequently been identified in medulloblastoma." (PMID 35328644, 2022). "Other studies have revealed that mutations in CTNNB1 and the accumulation of β-catenin are of good prognostic value for medulloblastoma patients." (PMID 36358663, 2022). "Most WNT medulloblastomas have mutations in exon 3 of the CTNNB1 gene which results in reduced cytoplasmic degradation and nuclear accumulation of B-catenin, a transcription factor coactivator." (PMID 36249063, 2022). "All samples in the Wnt subgroup had mutations in the third exon of the CTNNB1 gene, which is the most reliable single marker to identify Wnt-driven medulloblastoma." (PMID 34980884, 2022). "We report nine mutations in exon three of the CTNNB1 gene from WNT-activated medulloblastoma tumors from a cohort of 88 pediatric medulloblastoma patients." (PMID 35053583, 2022). "The results from a wave of medulloblastoma genome-sequencing studies revealed that DDX3X is the second most frequently mutated gene in medulloblastoma (8%, 25/300), followed by CTNNB1 (β-catenin)." (PMID 33627125, 2021). "WNT medulloblastoma, which accounts for 10% of all medulloblastomas, shows a loss of chromosome 6 and activating mutations in the CTNNB1 gene, encoding for β-catenin." (PMID 34577571, 2021). "The WNT-activated medulloblastoma (MB_1) showed characteristic variations specific for this subgroup, like a CTNNB1 mutation and chromosome 6 monosomy." (PMID 32758285, 2020). "Expression of the ALK gene strongly correlates with the WNT-activated medulloblastomas, which are routinely identified by detection of CTNNB1 mutation." (PMID 30523493, 2019). "Methylation subgrouping and CTNNB1 mutation status represent robust tools for the risk stratification of medulloblastoma." (PMID 24791927, 2014). "Molecular analysis of sporadic Wnt medulloblastomas commonly shows CTNNB1 mutations, which encode β-catenin." (PMID 25101241, 2014). "While the Frizzled receptor would make a possible target, the majority of mutations in medulloblastomas occur downstream of this by mutations in CTNNB1, which encodes for β-catenin." (PMID 25101241, 2014). "Because WNT-subtype medulloblastomas are associated with mutations in a gene named CTNNB1, the authors generated mice where this CTNNB1 gene would be deleted in certain hindbrain cell populations." (PMID 21427785, 2011). "A significant association between CTNNB1 nuclear immunoreactivity and survival has earlier been demonstrated in medulloblastoma, with nuclear accumulation being associated with a favourable outcome." (PMID 19293793, 2009). "The mutational status of APC and CTNNB1 (β-catenin) was investigated in 33 CNS PNETs and 22 medulloblastomas." (PMID 19293793, 2009). "In the medulloblastoma cohort, association between CTNNB1 nuclear immunoreactivity and percentage of cases that had relapsed almost reached significance (Fisher's exact test, P=0.056) with a lower percentage of relapses seen in the nuclear cases." (PMID 19293793, 2009). "Therefore, further studies with more extensive series from non-European populations are warranted to explore the clinical impact of CTNNB1 mutations in WNT-activated medulloblastomas." (PMID 37746264, 2023). "We observed that 73% of WNT-activated medulloblastomas harbored CTNNB1 mutations." (PMID 37746264, 2023). "Mutations in the β-catenin gene (CTNNB1) are often observed in medulloblastoma, which is the reason behind the deregulation of the Wnt pathway, which eventually leads to the increase in β-catenin levels and subsequent activation of genes that promote cellular proliferation, migration, and survival." (PMID 36358663, 2022).
medulloblastoma (continued). "Our findings are in line with previous data linking the up-regulation of the WNT/β-catenin signaling pathway to the development of certain brain tumors, e.g. medulloblastomas frequently harboring mutations in the CTNNB1 gene encoding β-catenin and glioblastomas." (PMID 33929593, 2021). "The gene for β-catenin (CTNNB1) is frequently mutated in WNT medulloblastomas." (PMID 29081735, 2017). "Mutations in CTNNB1 were identified in 4% of CNS PNETs and 20% of medulloblastomas." (PMID 19293793, 2009). "Four out of 20 primary medulloblastomas contained CTNNB1 mutations (20%)." (PMID 19293793, 2009). "The WNT subgroup of medulloblastoma is characterized by its distinct molecular profile, driven primarily by aberrations in the WNT signaling pathway, such as mutations in CTNNB1." (PMID 39851951, 2025). "In medulloblastoma, particularly the WNT subgroup, mutations in CTNNB1 (β-catenin) are prevalent, leading to aberrant pathway activation." (PMID 39851951, 2025). "The frequency of WNT-activated medulloblastomas with CTNNB1 wild type was significantly higher in Latin-Iberian population (27%) compared to those observed in NAM/EU populations (13%), (p=0.014769)." (PMID 37746264, 2023). "The Kaplan–Meier analysis showed that patients with WNT-activated medulloblastomas CTNNB1 wild type had worse outcome, with 71.4% of overall survival compared to 100% of CTNNB1 mutant cases (log rank: p=0.031)." (PMID 37746264, 2023). "It has been reported that 85%–90% of WNT-activated medulloblastomas harbor hotspot mutations in the CTNNB1 gene, which encodes beta catenin." (PMID 37746264, 2023). "WNT-activated medulloblastoma patients with CTNNB1 mutant showed an older median age at diagnosis of 11.3 years, compared with 10.0 years of CTNNB1 wild type, yet not statistically significant." (PMID 37746264, 2023). "A recent German study evaluated a large cohort of 191 WNT-activated medulloblastomas and reported 92.2% (176/191) CTNNB1 mutants and 7.8% (15/191) wild-type cases." (PMID 37746264, 2023). "We describe and functionally characterize a novel CTNNB1 in-frame deletion (c.109-111del, pSer37del, ΔS37) found in a pediatric patient with a classic medulloblastoma, WNT-activated grade IV." (PMID 35053583, 2022). "Beta-catenin is a central part of the Wnt signaling pathway and is encoded by the gene CTNNB1, which is frequently mutated in WNT medulloblastoma." (PMID 32056145, 2020). "When comparing methods for the identification of WNT-driven medulloblastoma, this study identified CTNNB1 sequencing and methylation profiling to most reliably identify these patients." (PMID 24791927, 2014). "Pathway activation through the stabilisation and nuclear accumulation of CTNNB1 has been shown in sporadic medulloblastomas." (PMID 19293793, 2009). "An association between CTNNB1 nuclear staining and CCND1 overexpression in the primary medulloblastomas just below significance was identified (Fisher's Exact Test, P=0.052)." (PMID 19293793, 2009). "CTNNB1 cellular location was also investigated in 46 medulloblastomas, including 43 primary samples." (PMID 19293793, 2009). "A high proportion of the medulloblastomas displaying nuclear CTNNB1 staining were of the desmoplastic subtype, which differs from earlier results." (PMID 19293793, 2009). "The ectopic WNT medulloblastoma (PB with WNT activation) showed nuclear β-catenin accumulation in only a small subfraction of tumor cells (< 5%), but a mosaic monosomy 6 and an activating CTNNB1 mutation." (PMID 41291966, 2025).
medulloblastoma (continued). "In addition, we analyzed the changes of proteins (APC, CTNNB1, DDX3X, PTEN, BCOR) associated with medulloblastomas in CB at the four developmental stages." (PMID 37400444, 2023). "Our findings contrast with other North American and European studies that did not observe any association of CTNNB1 status with WNT-activated medulloblastoma clinicopathological features." (PMID 37746264, 2023). "The patient was a 9.7-year-old girl diagnosed with WNT-activated, CTNNB1-wild type medulloblastoma." (PMID 37746264, 2023). "We found nine WNT-activated medulloblastomas CTNNB1 wild type in our Latin-Iberian population." (PMID 37746264, 2023). "In conclusion, the reported higher incidence of CTNNB1 wild type in our Latin-Iberian patients may be associated with a worse outcome and suggests a higher prevalence of hereditary WNT-activated medulloblastomas in this poorly characterized population." (PMID 37746264, 2023). "Considering that CTNNB1 wild-type cases may exhibit APC germline mutations, our study suggests a higher incidence (~30%) of hereditary WNT-activated medulloblastomas in the Latin-Iberian population." (PMID 37746264, 2023). "Importantly, the same mutation in CTNNB1 that drives oncogenic WNT signaling and tumorigenesis in WNT medulloblastomas also induces secretion of locally active WNT inhibitors, such as WIF1 and DKK1." (PMID 29081735, 2017). "CTNNB1 nuclear localisation was seen in 36% of CNS PNETs and 27% of medulloblastomas." (PMID 19293793, 2009). "Unlike medulloblastomas, pathway activation in CNS PNETs does not seem to be caused by mutations in exon 3 of CTNNB1, with only one CNS PNET in this study containing a mutation." (PMID 19293793, 2009). "A total of 10 out of 37 scorable primary medulloblastomas displayed CTNNB1 nuclear staining (27%)." (PMID 19293793, 2009). "The evidence, although significant, was not as strong in the medulloblastoma cohort, with 70% of tumours displaying nuclear localisation of CTNNB1 showing no CCND1 overexpression." (PMID 19293793, 2009). "The scorable and unscorable samples in the medulloblastoma cohort were very similar to the CTNNB1 and CCND1 analyses; therefore, no new comparison was made." (PMID 19293793, 2009). "They found that CTNNB1 deletion had no impact on the proliferation of ventricular zone cell or cerebellar granule cell precursor neurons (types of cells known to be affected in the SHH-subtype medulloblastoma)." (PMID 21427785, 2011).